ENG (endoglin)
Diseases named in the same sentence as ENG in open-access papers (continued):
Sharing a sentence is not in itself a finding about the gene and the disease.
tumor (continued). "In our previous studies, loss of endoglin in the tumor endothelium was found to be functionally linked to a facilitated transmigration of malignant cells across the vessel wall, and thereby an increased metastatic seeding, through the process of EndMT." (PMID 27741515, 2016). "Taken together, our analyses of compound RIP1-TAg2; Acvrl1+/−Eng+/− mice illustrates the utility of combinatorial targeting of ALK1 and endoglin in reducing hallmark parameters of tumor growth and progression." (PMID 27741515, 2016). "Increased levels of circulating soluble endoglin were linked to poor prognosis in different human tumours." (PMID 26296972, 2015). "As cellular ENG levels regulate the formation of new blood vessels, ENG antibodies have been successfully used to elicit anti-angiogenic effects in tumor-associated endothelium mouse models where ENG was highly expressed." (PMID 23341958, 2013). "A series of preclinical and clinical studies have indicated that endoglin is a hallmark molecule of tumor angiogenesis." (PMID 23209720, 2012). "CD105 (endoglin), a 180 kDa disulfide-linked homodimeric transmembrane protein, is one of the most suitable markers for tumor angiogenesis." (PMID 22174762, 2011). "In this review, we evaluate the implication of endoglin in tumor development underlying studies developed in our laboratories in recent years." (PMID 21170488, 2010). "Endoglin is overexpressed in the tumor-associated vascular endothelium, where it modulates angiogenesis." (PMID 21170488, 2010). "Thus, increased levels of endoglin in some cancer cells has been linked to tumor progression, malignant phenotype and metastasis; among others, in breast carcinoma, melanoma, or Ewing sarcoma." (PMID 41039222, 2025). "In addition, other research has indicated that ENG plays an oncogenic role in some cases and causes tumor growth and development, and in some cases it will result in tumor suppression." (PMID 39552710, 2024). "ENG dysfunction contributes to tumor associated angiogenesis and inflammation." (PMID 38242992, 2024). "Even though endoglin is predominantly expressed on endothelial cells, endoglin expression has also been observed in other cell types, including cancer-associated fibroblasts (CAFs), regulatory T cells, and epithelial tumor cells." (PMID 37396898, 2023). "In addition, several studies demonstrated that a high expression of endoglin in tumor tissues was an independent risk factor of lower 5-year overall survival rate." (PMID 36844233, 2023). "Recombinant L. monocytogenes-based vaccines expressing tumor-associated antigens (TAAs), including endoglin (CD105), human prostate-specific antigen (PSA), HER-2/neu, and HPV16 E7, have been developed for cancer immunotherapy in preclinical and clinical trials." (PMID 36838373, 2023). "The evaluation of ENG and MMP14 expression in a larger cohort of patient samples showed that high ENG levels were significantly associated with worse prognosis, suggesting that this protein could contribute tumor aggressiveness." (PMID 35955799, 2022). "ENG is thus an attractive therapeutic target for tumor-associated angiogenesis." (PMID 34830961, 2021). "Further studies should be carried out to determine the predominant ENG isoform in the tumor-associated macrophages (TAMs) associated with different cancer types to clarify its precise contribution to an anti-tumor M1-like or pro-tumor M2-like phenotype." (PMID 33804796, 2021). "ENG expression is specifically upregulated in actively proliferating ECs of tumor-associated vessels in different types of cancer, which has led to the use of ENG as a marker for tumor angiogenesis." (PMID 33804796, 2021). "Thus, endoglin is regarded as a potential novel tumor biomarker for patients with a high risk of developing HCC." (PMID 33809908, 2021).
tumor (continued). "Furthermore, an important role in vascular development and tumor-associated angiogenesis is represent by Endoglin, a transmembrane auxillary receptor for TGF-β that is predominantly expressed on proliferating endothelial cells." (PMID 33322134, 2020). "Furthermore, subgroup analysis revealed that the association between the overexpression of ENG in tumor microvessels and the outcome endpoints (OS or DFS) were also significant in the Asians and Caucasians patients with different cancer types." (PMID 29484142, 2018). "Moreover, endoglin-deficient ECs displayed features of endothelial-to-mesenchymal transition (EMT) in tumour vasculature, with enhanced signalling through the TGF-β RI/ALK5 pathway." (PMID 30563158, 2018). "Hence, increased endoglin expression in tumour ECs correlates with increased tumour growth (pro-angiogenic role), and its downregulation is associated with decreased tumour angiogenesis and growth." (PMID 30563158, 2018). "Down-regulation of endoglin caused reduced tumour growth in xenograft mouse models." (PMID 28030800, 2017). "Furthermore, the knockout of Gdf2 (BMP9), the primary ligand for ALK1 and endoglin, exhibited a mixed phenotype from each of ALK1 and endoglin deficiencies; overall primary tumor burden decreased, but hepatic metastases increased." (PMID 27741515, 2016). "Recently, several reports have shown that CD105 (EDG, endoglin), as a proliferation-associated and hypoxia-inducible protein, may be a good tumor MTS marker." (PMID 23202005, 2012). "In addition, accumulating evidence has demonstrated that endoglin is over-expressed and up-regulated in tumor-associated angiogenic vasculature relative to normal tissue vasculature." (PMID 23209720, 2012). "Endoglin is expressed not only by certain tumor cells but also by various cell types within the tumor microenvironment, including endothelial cells of the tumor vasculature, cancer-associated fibroblasts (CAFs), tumor-associated macrophages (TAMs), and tumor-associated lymphocytes (TALs)." (PMID 41039222, 2025). "Interestingly, several surface molecules exclusively expressed on metastatic UT-SCC-7 cell-derived EVs were associated with cancer progression, for example, CD105 (endoglin), which has a crucial role in angiogenesis and its elevated level is correlated with tumor metastasis." (PMID 37495566, 2023). "However, the function of ENG in tumor-associated mast cells has yet to be established." (PMID 33804796, 2021). "Thus, ENG is a potential marker of tumor-associated angiogenesis and prognosis." (PMID 34944885, 2021). "Similarly, it has been reported that the CD105 (endoglin) antibody was available for antiangiogenic tumor therapy, and that microtubule-associated protein-2 (MAP-2) antibody could elevate the therapeutic efficacy in spinal cord injury." (PMID 33066531, 2020). "To seed tumor cells at metastatic sites, we injected fluorescently labeled control and endoglin KD HT1080 cells intravascularly." (PMID 41532547, 2026). "These markers, including vasohibin-1 (VASH-1), CD31, and endoglin, can predict tumor progression and prognosis." (PMID 40565098, 2025). "Taken together, these findings indicate ENG expressed on myCAFs is required for their tumor‐ and metastasis‐promoting ability." (PMID 40644310, 2025). "Flow cytometry detecting the cell‐surface ENG protein also showed an increasing proportion of upregulated ENG‐positive cells in exp‐CAFs during tumor progression." (PMID 40644310, 2025). "We selected CD105/Endoglin, a well-established marker of tumor angiogenesis, for simultaneous immunostaining." (PMID 41374934, 2025). "For tumours with mutations KLF4K409Q/TRAF7, Endoglin, E-cadherin and Anion exchange protein 2 were selected for further validation by Western blot." (PMID 40562609, 2025). "Collectively, these data demonstrate that ENG is expressed by myCAFs and vascular ECs in the tumor stroma." (PMID 40644310, 2025).
tumor (continued). "Four primary cell populations were first identified using canonical cell markers: WT tumor cells (WT1, NCAM1, SIX1, SIX2, PAX2), cancer-associated fibroblasts (CAFs) (ACTA2, TAGLN, COL1A1, PDGFRB), endothelial cells (PECAM1, CLDN5, ENG, VWF) and immune cells." (PMID 40098972, 2025). "Collectively, these data indicate that ENG expression is required for CAFs to promote tumor cell proliferation, angiogenesis, neutrophil infiltration, and ECM remodeling in tumors." (PMID 40644310, 2025). "In this context, it needs to be pointed out that although endoglin was initially identified on ECs, more recent work has shown that a wide variety of other cell types, including tumor cells, immune cells, and fibroblasts can as well express endoglin." (PMID 41378712, 2025). "Although we observed that increased ENG expression in myCAFs mediates their tumor‐ and metastasis‐promoting ability, precisely how ENG expression is upregulated in these fibroblasts remains an unresolved issue." (PMID 40644310, 2025). "The potential of these compounds to target complex diseases linked to TGFβ1 and endoglin motivates their use in combination with PDT, with the aim of enhancing treatment efficacy by mitigating tumor resistance 17-19." (PMID 40384860, 2025). "Our data suggest that MerTK regulates a unique proliferative signature in TNBC, promoting robust tumor growth and increased metastatic potential through ENG upregulation." (PMID 38791148, 2024). "Some previous investigations mentioned the impacts of endoglin on angiogenesis and tumor development." (PMID 39552710, 2024). "Endoglin overexpression has been shown to lead to activation of endothelial cells in tumour tissues which is correlated to metastasis." (PMID 38168704, 2024). "In summary, we found a significant correlation between ENG expression and tumor-immune systems among pan-cancer (red colors)." (PMID 39247590, 2024). "In summary, our investigation revealed that MerTK regulates a unique proliferative signature, allowing for robust tumor growth and increased metastatic potential via the regulation of ENG." (PMID 38791148, 2024). "ENG, as an endothelial glycoprotein gene, has been known for its essential role in many tumors with the potential as a target for tumor therapy." (PMID 38233508, 2024). "Endoglin, also known as CD105, interacts with TGFβRI and TGFβRII and plays a role in metastasis formation in various types of cancer mainly through its involvement in primary tumor angiogenesis." (PMID 38761292, 2024). "There were, however, concerns regarding an increased expression of endoglin on tumor EC relative to normal EC." (PMID 39766150, 2024). "ENG is likely to be a novel target for tumor immune response and immunotherapy, and CD likely suppresses BC growth and metastasis at least partially through upregulating tumor suppressor gene ENG expression." (PMID 39247590, 2024). "Endoglin, another endothelial cell marker crucial for tumor growth regulation, has also been targeted for anti-angiogenic vaccination." (PMID 39081320, 2024). "Our results indicated that the ENG level increases in a dose-dependent fashion upon CD treatments, suggesting that CD likely suppresses BC tumor growth and metastasis, at least partially through upregulating tumor suppressor gene ENG expression." (PMID 39247590, 2024). "Our analysis revealed that ENG expression is significantly correlated with tumor-immune systems among pan-cancer." (PMID 39247590, 2024). "Since in the present study, ENG downregulation apparently indicates the critical role of ENG as a tumor suppressor in the relevant tissue, and the reduction of its expression has led to the development of UCEC." (PMID 39552710, 2024). "In a model of MerTK overexpression, we identified the upregulation of endoglin (ENG), a small transmembrane receptor for TGFβ, as a key determinant of tumor metastasis in vivo." (PMID 38791148, 2024).
tumor (continued). "Endoglin was highly expressed in both TNBCs and is in vivo responsible for a cold tumor phenotype by preventing angiogenesis, inflammation and accumulation of cancer-associated fibroblasts." (PMID 38896334, 2024). "In this review we discuss the role of endoglin as a possible marker of carcinogenesis, as well as a potential target for antibody-based therapies in the neoplasms of the head and neck region." (PMID 36844233, 2023). "Intra-tumour micro-vessel density assessed by endoglin/CD105 staining has been shown to strongly correlate with prognosis in many cancer patients." (PMID 37052868, 2023). "Endoglin expression on epithelial tumor cells, however, has been a subject of debate for some years, with a limited number of published studies." (PMID 37396898, 2023). "TRC105 (TRACON Pharmaceuticals Inc.)is a chimeric IgG1 anti-endoglin antibody, that induces apoptosis in endoglin-positive tumor cells." (PMID 36844233, 2023). "Endoglin expression increases in areas where vascular injury and active angiogenesis are taking place, in both tumor and non-tumor cells." (PMID 36927633, 2023). "We here established, in the context of AML, that high‐stromal endoglin is required to support in trans the gain of tumor translational activity induced by stromal syntenin deficiency (EV2C and 7C)." (PMID 37819151, 2023). "Most of the examined tumors exhibited negative-to-weak endoglin staining but a statistically significant correlation was found between tumor local recurrence and endoglin expression." (PMID 36844233, 2023). "It was demonstrated that MVD assessed on the basis of endoglin immunohistochemical expression in the tumor tissue correlated with poor prognosis in colorectal, breast, prostatic and lung cancer patients." (PMID 36844233, 2023). "Endoglin is implicated in angiogenesis while EV‐associated VEGF has been demonstrated to promote angiogenesis around tumours." (PMID 37337371, 2023). "This molecular finding gains value given prior mechanistic knowledge of upregulation of endoglin expression on tumor endothelial cells in response to VEGF inhibition." (PMID 37684373, 2023). "Future research directions in this area should also include studies on a soluble form of endoglin as a potential marker of tumor progression and recurrence." (PMID 36844233, 2023). "In conclusion, these data show endoglin expression on individual cells in the tumor nests in SCCs and a role for (soluble) endoglin in paracrine signaling, without directly affecting proliferation or migration in an autocrine manner." (PMID 37396898, 2023). "Further work should reveal the role of (soluble) endoglin in paracrine signaling in the tumor microenvironment of SCCs." (PMID 37396898, 2023). "In multiple types of cancer, it has been shown that a high endoglin expression on tumor vessels is correlated with a worse clinical outcome." (PMID 37396898, 2023). "Immunohistochemical analysis showed high endoglin expression on newly formed blood vessels, as previously reported, together with tumor type dependent staining of stromal cells in all SSCs evaluated." (PMID 37396898, 2023). "This indicates that individual tumor cells express endoglin, alongside with endoglin expression by macrophages." (PMID 37396898, 2023). "This is in contrast with previous findings that endoglin (ENG) was reported to be a tumor-suppressing gene in ESCC." (PMID 37396898, 2023). "RES downregulated both mRNA and protein levels of endoglin (ENG), a crucial protein in angiogenesis, in HCC827 cells in vitro, but also in vivo as was demonstrated by endoglin-positive staining of tumor tissue sections." (PMID 37175156, 2023). "A recent study projects endoglin as a crucial molecule in the determination of an immunosuppressive tumour microenvironment, mainly because of its role on angiogenesis but also in inflammation and in cancer-associated fibroblast (CAFs) biology." (PMID 37052868, 2023).
tumor (continued). "GSVA scores showed that inflammatory response was upregulated in these cells, indicating that ENG expression in CAFs serve as an indicator of fibroblasts contribution to tumor growth." (PMID 37533434, 2023). "CD105 (Endoglin), which is predominantly expressed by endothelial cells and is involved in tumor angiogenesis, showed higher protein expression in HHSEC cells in four cell lines after co-culture." (PMID 37240247, 2023). "One of the promising targets is CD105 (endoglin), a transforming growth factor coreceptor that is crucial in developmental biology and tumor angiogenesis." (PMID 36769077, 2023). "Since it results in being specifically expressed on active endothelial cell surfaces, Endoglin (CD105) has been proposed as a reliable marker for MVD assessment in neoplasms." (PMID 37445908, 2023). "Endoglin expression is also up-regulated on tumor endothelial cells in response to inhibitors of the VEGF pathway and allows continued tumor growth." (PMID 37684373, 2023). "Next to being expressed on angiogenic endothelial cells, endoglin is selectively expressed by individual SCC cells in tumor nests." (PMID 37396898, 2023). "We focussed on endoglin, enolase γ, VEGF, IL‐6 and CCL20 which were all enriched in TSC2‐ EVs, compared to TSC2+ EVs, due to known associations with tumour‐promoting functions." (PMID 37337371, 2023). "The highest density of endoglin-positive blood vessels was also observed in tumor stromal areas with marked inflammation." (PMID 36844233, 2023). "There was a mice experiment indicating that anti-ENG monoclonal antibody in treatment can suppress tumor progression." (PMID 36245844, 2022). "IFN-γ, IGFBP-1, IL-23, Endoglin and Serpin E1 were elevated in tumor-bearing serum at both timepoints." (PMID 35962398, 2022). "Several molecules, particularly the OC-associated vascular endothelial cell-associated transmembrane glycoproteins including endoglin (CD105) and integrin αvβ3 are expressed predominantly on tumor endothelial cells that are undergoing active angiogenesis." (PMID 36132133, 2022). "NGS analysis showed that endoglin overexpression in DEHP-exposed MDA-MB-231 cells correlated with tumor development and growth." (PMID 35203627, 2022). "Endoglin (CD105) is a membrane receptor found on endothelial cells that are highly expressed in the proliferating tumor vasculature." (PMID 36293428, 2022). "Endoglin (CD105) is a protein produced in activated endothelial cells during inflammatory and tumoral settings, and it has therefore been utilized to assess tumor angiogenesis in a variety of premalignant and malignant conditions." (PMID 36497464, 2022). "Endoglin is mainly found in immature tumor vascular endothelial cells and contributes to tumor angiogenesis." (PMID 35000616, 2022). "As a marker for tumor diagnosis, prognosis, and therapy, Endoglin/CD105 is involved in vascular development and remodeling by enhancing cell proliferation and migration." (PMID 35806196, 2022). "TRC105, an IgG1 endoglin monoclonal antibody (MAb), has been found to diminish tumor metastasis by inhibiting endoglin-modulated angiogenesis." (PMID 35409247, 2022). "Significant evidence has shown increased endoglin in the TGF-β signaling pathway in tumor-associated endothelial cells, making it ‘a marker’ for tumor-induced angiogenesis." (PMID 35203627, 2022). "In addition, tumor-related angiogenesis may be caused by endoglin dysregulation." (PMID 35409247, 2022). "We found that TGFB1 and its binding partner ENG were both highly expressed in tumor cells and TGFB1-ENG gene pair occupied a key position in the network." (PMID 36249427, 2022). "Tumor samples presented extensive homogenous protein levels of both ENG/MMP14 on the TMA sections and thus were evaluated by intensity only." (PMID 35955799, 2022). "Section 3 will discuss the general function of endoglin in cancer, including its role in angiogenesis and other processes, and the rationale of using endoglin as target for tumor imaging." (PMID 33946583, 2021).